OR52A1 (olfactory receptor family 52 subfamily A member 1)
Description:
Odorant receptor.
Synonyms: HPFH1OR
Tractability: Antibody: its Gene Ontology location is reachable by antibodies, with high confidence; UniProt places it where antibodies can reach, with medium confidence; UniProt predicts a signal peptide or a membrane-spanning region.
Gene: Protein-coding gene on chromosome 11 (5,146,824 to 5,154,757, reverse strand). Ensembl gene ENSG00000182070.
Subcellular location: Cell membrane
Pathways (Reactome):
Sensory Perception: Expression and translocation of olfactory receptors
Gene Ontology:
Molecular function: olfactory receptor activity; transmembrane signaling receptor activity; G protein-coupled receptor activity
Biological process: sensory perception of smell; signal transduction; detection of chemical stimulus involved in sensory perception of smell; G protein-coupled receptor signaling pathway; nervous system process
Cellular component: plasma membrane; membrane
Genetic constraint (gnomAD): Loss-of-function variants: 14 observed, 14.81 expected, observed/expected ratio (o/e) 0.95, 90% interval 0.62 to 1.47. The upper end of that interval is the gene's LOEUF score, 1.47, which puts it in group 6 of 6, group 1 being the genes least tolerant of losing a copy. Missense variants: 385 observed, 379.92 expected, observed/expected ratio (o/e) 1.01, 90% interval 0.93 to 1.1. Synonymous variants: 142 observed, 135.49 expected, observed/expected ratio (o/e) 1.05, 90% interval 0.91 to 1.21.
Homologues: Orthologues: chimpanzee OR52A1 (98% identical), macaque OR52A1 (96% identical). Paralogues in human: OR52A5 (74% identical), OR52R1 (50% identical), OR52E2 (49% identical), OR52N4 (49% identical), OR52E8 (49% identical), OR51E2 (49% identical), OR52E4 (48% identical), OR52L1 (48% identical), OR52E6 (47% identical), OR52K2 (47% identical), OR52K1 (47% identical), OR52N1 (47% identical), and 39 more.
Diseases named in the same sentence as OR52A1 in open-access papers:
OR52A1 is named in the same sentence as 3 diseases in open-access papers, as found by Europe PMC text mining. Sharing a sentence is not in itself a finding about the gene and the disease. The quoted sentences say what the papers report.
anemia (2 papers, 2011 to 2025). A reduction in the number of red blood cells, the amount of hemoglobin, and/or the volume of packed red blood cells. "In addition, one of the olfactory genes in this region, OR52A1, contains an enhancer for γ-globin, and variants that disrupt the function of this enhancer may exacerbate anemia in individuals with thalassemia." (PMID 40306283, 2025). "Of particular interest to β-thalassemia is OR52A1, which was previously shown to contain a γ-globin enhancer element that confers continuous expression of the two fetal γ-globin genes that are overexpressed in β-thalassemia and tend to alleviate the anemia by increasing hemoglobin F production." (PMID 21390308, 2011).
OR52A1 also shares sentences with these, for which no sentence is quoted: thalassemia (2 papers); sickle cell anemia (1).